TIMP1 (TIMP metallopeptidase inhibitor 1)
Diseases named in the same sentence as TIMP1 in open-access papers (continued):
Sharing a sentence is not in itself a finding about the gene and the disease.
Skin ulcer (1 paper, 2021). A discontinuity of the skin exhibiting complete loss of the epidermis and often portions of the dermis and even subcutaneous fat. "Besides, IGF-I treatment helped to restore the normal expression of both matrix metalloproteinase (MMP)-9 and tissue inhibitors of metalloproteinase (TIMP)-1 in diabetic rats with skin ulcers, indicating an important role of IGF-I in healing." (PMID 33860062, 2021).
spinal stenosis (1 paper, 2022). Narrowing of the spinal canal. "This hypothesis was confirmed by the significant association between elevated TIMP-1 and TIMP-2 expression in LF fibroblasts and spinal stenosis, a reproducible finding of several different experiments of various methods." (PMID 36269774, 2022).
supravalvular aortic stenosis (1 paper, 2023). SupraValvar Aortic Stenosis (SVAS) is characterized by the narrowing of the aorta lumen (close to its origin) or other arteries (branch pulmonary arteries, coronary arteries). "Reduction of elastin synthesis by VSMCs in Williams Beuren Syndrome and supravalvular aortic stenosis is associated with dysregulation of MMP-9/tissue inhibitor of metalloproteinase-1 (TIMP-1) leading to enhanced elastolytic capability." (PMID 37001705, 2023).
tongue cancer (1 paper, 2019). A malignant neoplasm affecting the tongue. "ANE also stimulates MMP-9, but decreases tissue inhibitor metalloproteinase-1 (TIMP-1) and TIMP-2 secretion of SAS tongue cancer epithelial cells." (PMID 31831717, 2019).
toxicity (1 paper, 2014). The degree to which an agent can damage an organism. "Levels of TIMP-1 at 24-hours were significantly elevated in patients with severe lung toxicity compared to those without." (PMID 25289758, 2014).
Urethral stricture (1 paper, 2019). Narrowing of the urethra associated with inflammation or scar tissue. "Alpha-smooth muscle actin (α-SMA) and tissue inhibitor of metalloproteinases (TIMP-1) have been shown to induce fibrosis by their upregulation at molecular level in various fibrotic conditions including urethral stricture." (PMID 31579841, 2019). "Urethral stricture had higher levels of TIMP-1 expression and correlated with increased collagen levels." (PMID 31579841, 2019). "Hence, in this study, we evaluated the effect of HAMECs-CM on urethral stricture fibroblast (USF) cells using in vitro scratch assay and gene expression of α-SMA and TIMP-1." (PMID 31579841, 2019).
Urothelial cell carcinoma (1 paper, 2008). "Urothelial cell carcinoma cell lines were cultured with synthetic and physiological protease inhibitors, including BB94, aprotinin, TIMP1 and TIMP2, and invasion was assessed by the Matrigel assay." (PMID 18665176, 2008).
vascular tumors (1 paper, 2018). "Our earlier studies have shown that over-expressing TIMP-1 in NSCLC cell line H2009, resulted in more aggressive and vascular tumors in mice compared to controls." (PMID 29507665, 2018).
ventricular fibrillation (1 paper, 2023). A disorder characterized by an electrocardiographic finding of a rapid grossly irregular ventricular rhythm with marked variability in QRS cycle length, morphology, and amplitude. "TIMP-1 and IL-8 have been identified as markers that indicate ventricular fibrillation in MI patients." (PMID 36197585, 2023).
Vertigo (1 paper, 2019). An abnormal sensation of spinning while the body is actually stationary. "On the other hand, the TIMP-1 serum level was markedly higher in vertigo patients with high grade WMH (grade 2 and 3) (n = 85) than those with low grade WMH (grade 0 and grade 1) (n = 127) (P < 0.01)." (PMID 31474817, 2019). "In vertigo patients, we found various probably associations between MMP-9 and TIMP-1 with arterial alterations linked to both VBD and WMH that may help with the diagnosis and treatment of such diseases in the future." (PMID 31474817, 2019). "However, in the current study, MMP-2, -3 or -9 levels were not higher in vertigo patients with LI or advanced stages of WMH, whereas the TIMP-1 level was higher in vertigo patients with higher WMH grades (grade 2 and 3)." (PMID 31474817, 2019). "MMP-9 and TIMP-1 serum levels were both higher in vertigo patients with VBD, and we further found that upregulation of MMP-9 might be accompanied by the downregulation of TIMP-1 but not by TIMP-2 regulation." (PMID 31474817, 2019). "MMP-9 serum level was significantly higher in vertigo patients with VBAs dilation and basilar artery (BA) elongation compared to those with healthy arterial size, and the ratio of MMP-9/TIMP-1 level were higher in those patients." (PMID 31474817, 2019). "We found that MMP-9 serum level was higher in vertigo patients with VBA dilation and BA elongation, and the ratio of MMP-9/TIMP-1 level were higher in those patients, while TIMP-1 serum level was higher in those patients with BA tortuosity." (PMID 31474817, 2019). "We did, however, identify a near significant difference in the TIMP-1 serum level, being higher in vertigo patients with LI compared to those without LI (P < 0.10)." (PMID 31474817, 2019). "TIMP-1 level was also markedly higher in vertigo patients with BA tortuosity than those without BA tortuosity." (PMID 31474817, 2019).
Zinc deficiency (1 paper, 2025). A deficiency of the essential metal Zinc; an essential cofactor for many enzymes. "Our qPCR results demonstrate a significant increase in mRNA expression levels of TIMP-1 and PAI-1 under zinc deficiency condition, while the expression of MMP-2 decreased." (PMID 39028478, 2025).
tumor (740 papers, 1992 to 2026). "Conversely, knockdown of TIMP1 using two independent shRNA constructs (shTIMP1-1 and shTIMP1-2) significantly reduced liver metastatic burden and tumor-associated liver enlargement." (PMID 41511313, 2025). "Classically regarded as an inhibitor of tumor progression, TIMP-1 upregulation has consistently been associated with poor prognosis in all cancers across the board." (PMID 41002380, 2025). "High TIMP1 histoscore in both tumor epithelial and stromal cells strongly associated with proximal tumor location, MMR deficient status, and BRAF mutation (all p < 0.001)." (PMID 39789100, 2025). "In this study, BRAF status and proximal tumor location associated with both high TIMP1 serum levels and TIMP1 expression in tumor tissue." (PMID 39789100, 2025). "High TIMP1 intensity in tumor stroma associated with longer cancer-specific and overall survival in univariable analysis but not in multivariable models." (PMID 39789100, 2025). "Serum TIMP1 levels were evaluated for correlations with tumor TIMP1 expression, and their associations with tumor characteristics, inflammation, and prognosis were investigated." (PMID 39789100, 2025). "We explored the correlation between serum and tumor TIMP1 levels and investigated their associations with tumor characteristics, inflammation, and prognosis." (PMID 39789100, 2025). "TIMP-1 is on MMP inhibitor, but also an independent growth factor, and elevated levels of TIMP-1 have been found to correlate with poorer prognosis of several cancers and to associate with tumor stage and progression." (PMID 39917664, 2024). "TIMP1 was found to be upregulated in tumor samples, and this elevated expression was associated with higher TNM categories, advanced cancer stages, and grades." (PMID 38802480, 2024). "Numerous clinical studies have demonstrated that abnormal expression of TIMP1 is associated with an adverse prognosis in various tumours." (PMID 37688768, 2023). "Even so, TIMP-1-expressing cells are more resistant to chemotherapy than are TIMP-1 gene-deficient, and in CRC patients, high levels of TIMP-1 in tumor tissue and plasma are strongly associated with shorter survival time." (PMID 36982144, 2023). "Altogether, these data indicate that specific mutations regulate the expression of TIMP1/CD44v6 complex, which sustain the tumor growth of the different TC histotypes through the activation of PI3K/AKT pathway." (PMID 36906579, 2023). "TIMP1 exerted a tumor-promoting role in ccRCC and was significantly associated with immunosuppressive cells and checkpoints." (PMID 37688768, 2023). "At last, the tumor-promoting and tumor-associated macrophage polarization roles of TIMP1 in LGG were validated by in vitro experiments." (PMID 37264314, 2023). "According to an earlier study, aggressive tumor phenotypes were strongly associated with the abnormal expression of TIMP1 in COAD33." (PMID 37497410, 2023). "More importantly, in vitro experiments, we further confirmed the polarizing effect of TIMP1 on tumor-associated macrophages." (PMID 37264314, 2023). "Similar results were obtained by analyzing the association between the expression of the studied genes in tumor samples and patient survival (TIMP1, p = 0.5972; MMP2, p = 0.9627; MMP9, p = 0.8563)." (PMID 37509417, 2023). "A high TIMP-1 protein expression level has been shown to be positively associated with poor prognosis or tumor progression." (PMID 37509417, 2023). "TIMP-1 has been mainly detected in tumor cells, vascular endothelium, and carcinoma-associated fibroblasts in HNSCC, thereby acting at the interface between the tumor microenvironment and the tumor’s systemic connection." (PMID 36551979, 2022). "Studies in CRC have indicated that upregulation of TIMP1 was associated with poor prognosis and confirmed that TIMP1 can promote tumor cell proliferation and metastasis through the FAK/Akt signaling pathway." (PMID 36338624, 2022).
tumor (continued). "For instance, tumor-associated macrophages (TAMs) have been found to express TIMP-1 depending on their phenotype." (PMID 36291767, 2022). "On the other hand, we also detected that TIMP1 was particularly connected with the immune marker of tumor-associated macrophage, macrophage M1, macrophage M2, neutrophils, and Tregs." (PMID 35685428, 2022). "Among four TIMPs, TIMP1 overexpression or TIMP3 silencing is considered to be associated with tumor progression." (PMID 35559040, 2022). "The proteins Hsp70 and TIMP-1 are linked to the tumor microenvironment in HNSCC patients and are secreted by the salivary glands." (PMID 36551979, 2022). "Among other top ascorbate-mediated protein increases were extracellular matrix remodeling proteins such as MMP-2 and TIMP-1 which are associated with tumour metastasis and poor prognosis." (PMID 33799728, 2021). "In fact, it has been reported that TIMP-1 and -2 are significantly higher in tumor samples and associated with a poor prognosis in CRC." (PMID 33946534, 2021). "Elevated tumor tissue TIMP1 levels were significantly associated with a poor response to chemotherapy." (PMID 34737677, 2021). "This is why we can observe that TIMP1 elevation is associated with the poor prognosis of human tumours in many clinical trials." (PMID 35003085, 2021). "TIMP1 expression was negatively associated with tumour purity but positively correlated with dendritic cells." (PMID 34781885, 2021). "In CRC samples, immunostaining for MMP-7, MMP-14 and TIMP-1 were localized primarily in tumor cells, but also in stromal cells (cancer-associated fibroblasts (CAF) as well as MICs)." (PMID 33946534, 2021). "TIMP1 deficiency increases either tumor cell sensitivity to chemotherapy or TNF-α-induced apoptosis." (PMID 34737677, 2021). "When targeting TIMP1‐deficient senescent tumour cells with ABT‐263, the authors showed that the metastatic potential was significantly reduced." (PMID 34137158, 2021). "TIMP1 can promote the aggregation of tumor-associated fibroblasts in the body and promote the proliferation and migration of cancer cells, and has antiapoptotic function." (PMID 33015179, 2020). "While TIMP-1 is primarily known as an endogenous inhibitor of matrix metalloproteinases (MMPs) and thus associated with tumor cell invasion, clinical studies demonstrated increased expression of TIMP-1 and its association with poor prognosis in cancer." (PMID 32034211, 2020). "Associations between coexpression of MMP-7 and TIMP-1 in tumour tissues and the survival of GC patients were evaluated by a stratified analysis of age group, T stage, N stage, and chemotherapy." (PMID 33005257, 2020). "The results showed that age group, T stage, N stage, chemotherapy, and coexpression of MMP-7 and TIMP-1 in tumour tissues were associated with patient survival." (PMID 33005257, 2020). "In a recent study, this adverse relation has been linked to TIMP-1 inhibition of tumor cell death by activating phosphoinositide 3-kinases (PI3Ks), which are responsible for AKT/ERK phosphorylation." (PMID 32466129, 2020). "In line with this evidence, expression of representative IL-6-mediated STAT3 target genes such as Socs3 and Timp1 were largely unaltered in tumor livers of lean IL-6Rα-deficient mice compared to controls." (PMID 30224299, 2018). "Intriguingly, dysregulation of TIMP1 caused by both abnormal miR-122 silencing and hypermethylation is involved in tumor proliferation." (PMID 30344796, 2018). "More importantly, high expression of CXCL3, ELF5, and TIMP1 was significantly associated with lymphatic invasion, distance metastasis, and advanced tumor stage." (PMID 29209625, 2017). "Our further experiment about validation and clinicopathologic analysis revealed that high expression of CXCL3, ELF5, and TIMP1 was significantly associated with lymphatic invasion, distance metastasis, and advanced tumor stage." (PMID 29209625, 2017).
tumor (continued). "TIMPs have been strongly implicated as potential markers in the diagnosis of pancreatic cancer; in particular, TIMP1 is associated with tumor metastasis and has long been a protein of interest." (PMID 28514751, 2017). "As a cytokine and a key regulator of ECM degradation, TIMP-1 has multiple functions associated with the tumor microenvironment and cancer progression." (PMID 27130446, 2016). "For example, in breast cancer patients, high tumor and serum levels of TIMP-1 have been associated with decreased response to chemotherapy and consequently reduced survival." (PMID 25600295, 2015). "This study has demonstrated that tumor-associated HSCs secrete TIMP-1 and affect the proliferation, motility, and anchorage-independent growth of HCC cells." (PMID 26549110, 2015). "Many publications support the link between MM9, TIMP-1 and tumor cell survival demonstrating a high statistically significant association between high tumor or plasma levels of TIMP-1 and poor cancer patient outcome." (PMID 27275301, 2015). "Song and colleagues reported that TIMP-1 activates carcinoma-associated fibroblasts and suppresses tumor apoptosis via SDF-1/CXCR4 signaling, which promotes HCC progression." (PMID 26549110, 2015). "In contrast, TIMP-1 expression displays a tendency to increase in association with higher tumor grades, while TIMP-3 and -4 have a tendency to decrease." (PMID 26431549, 2015). "Neutrophil-derived gelatinase B/MMP-9 involvement in tumour-associated intravasation requires neutrophil attraction to the activated endothelial cell surface, neutrophil activation and release of TIMP-1-free gelatinase B/MMP-9." (PMID 24473089, 2014). "Consistent with this pro-tumorigenic role of TIMP-1, several clinical studies have demonstrated that elevated TIMP-1 levels in tumor tissue or peripheral blood are associated with poor clinical outcomes in a range of malignancies." (PMID 24978435, 2014). "Together, these results establish the potential of TIMP-1 as a novel target for cancer therapy and the mechanism underlying the pro-tumor activity of TIMP-1." (PMID 24143225, 2013). "We can assume that elevated TIMP-1 levels reflect the degree of proteolytic activity which is an essential process implicated in invasiveness of tumour cells." (PMID 23801910, 2013). "Stromal MS-5 interaction induced up-regulation of MIP-2, MIP1α, RANTES, and TIMP-1 that are associated with tumor progression." (PMID 24265713, 2013). "Our results indicating an association between TIMP-1 expression and higher tumour grade were especially remarkable." (PMID 20160732, 2010). "Adenoviral delivery of TIMP-3 gene inhibited the growth of pre-established A549 tumours in Balb/c nude mice, and was associated with a greater therapeutic effect than either TIMP-1 or -2 gene delivery." (PMID 21152266, 2010). "Increased expression of TIMP-1 has been associated with unfavourable outcome in several tumor types." (PMID 20388222, 2010). "In the subgroup of CMF-treated patients, however, we found an association between TIMP-1 and hormone receptor status with higher tumor tissue TIMP-1 levels in patients with hormone receptor negative tumors (Mann-Whitney test, P = 0.04)." (PMID 19744322, 2009). "Despite the small size of the anthracycline-treated subgroup, the analysis of DFS clearly indicated an association between high levels of tumor tissue TIMP-1 and a shorter survival." (PMID 19744322, 2009). "We then compared the outcome after therapy and the association with increasing tumor tissue TIMP-1 separately within each treatment subgroup (anthracycline-treated, CMF)." (PMID 19744322, 2009). "These include studying the effect of chemotherapeutic drugs on tumours induced by inoculation of our cells in the TIMP-1 gene-deficient and wild-type BALB/cJ mouse strain." (PMID 17047657, 2006).